CRX (cone-rod homeobox)
Diseases named in the same sentence as CRX in open-access papers (continued):
Sharing a sentence is not in itself a finding about the gene and the disease.
retinal degeneration (16 papers, 2010 to 2026). Degeneration of the retina. "Mutations in several other genes such as GUCY2D, RHO, CRX, etc., are also associated with both dominant and recessive retinal degeneration, but the situation is a little different for them." (PMID 33681214, 2021). "FAM161A has been shown to interact with the CRX (Cone-rod homeobox-containing) transcription factor and Lebercilin, both of which have also been implicated in retinal degeneration in humans." (PMID 24705771, 2014). "The vertebrate homologs of Otd are involved in retinal development, including OTX1, OTX2 and CRX (‘cone rod homeobox’), whose mutations cause retinal degeneration." (PMID 24625735, 2014). "In fact, the association of CRX mutations, which may cause severe forms of retinal degeneration like LCA, with apparently mild clinical pictures like sector or pericentral RP may be of interest for correct genetic counseling." (PMID 38792980, 2024). "CRX was the first photoreceptor transcription factor identified to cause retinal degeneration." (PMID 38049871, 2023). "We have performed single cell RNA‐seq of the CRX+ precursors to assess intercellular heterogeneity and in parallel we have tested their engraftment into an animal model of early onset severe retinal degeneration (Pde6brd1)." (PMID 30681766, 2019). "The question arises as to why these CRX+ cells mature into cones upon transplantation into this animal model of retinal degeneration." (PMID 30681766, 2019). "The blind children with LCA manifest severe retinal degeneration, a phenotype typical for CRX and LCA." (PMID 29568065, 2018). "The interaction between ATXN7 and CRX has been hypothesised to be a key factor behind the development of retinal degeneration in SCA7 patients." (PMID 33626063, 2021). "In addition, two proteins are known to suppress CRX functions and promote retinal degeneration: ataxin 7 and BAF." (PMID 34298993, 2021). "Together, these data suggest that graft‐host integration occurs within the 3 weeks post‐transplantation, and that hESC‐derived‐CRX+ photoreceptor precursors are a promising resource for cone photoreceptor cell replacement in a mammalian model of retinal degeneration." (PMID 30681766, 2019). "Finally, spatial differences in CRX expression may contribute to accelerated retinal degeneration in areas with higher expression." (PMID 41595470, 2026). "It has been postulated that retinal degeneration in SCA7 may be associated with an abnormal interaction between the expanded ataxin-7 and CRX as potentially binding the expanded polyQ tract in ataxin-7 to a glutamine-rich region in CRX." (PMID 32973440, 2020). "CRX transduced by SeV acts as a master control gene for reprogramming of PBMCs into photoreceptors and the induced photoreceptor-like cells we generated might contribute to individualized drug screening and disease modeling of inherited retinal degeneration." (PMID 27170256, 2016). "Haplo-insufficiency would thus not play a role in CRX-induced retinal degeneration under this model of action." (PMID 29568065, 2018).
retinitis pigmentosa (12 papers, 2017 to 2026). Retinitis pigmentosa (RP) is an inherited retinal dystrophy leading to progressive loss of the photoreceptors and retinal pigment epithelium and resulting in blindness usually after several decades. "Wdr17 is a candidate for the RP29 form of Retinitis Pigmentosa and has binding sites for CRX and NRL close to the rod TSS." (PMID 28640837, 2017). "In this study, we investigated the transcriptional profile of CRX‐expressing photoreceptor precursors derived from human pluripotent stem cells and their engraftment capacity in an animal model of retinitis pigmentosa (Pde6brd1), which is characterized by rapid photoreceptor degeneration." (PMID 30681766, 2019).
retinal disease (11 papers, 2014 to 2026). "Background/Objectives: Genetic variants in the cone–rod homeobox (CRX) gene, a transcription factor critical for the differentiation, function, and survival of photoreceptors, are a rare cause of inherited retinal diseases (IRDs)." (PMID 41595470, 2026). "Mutations in CRX cause a spectrum of retinal disease phenotypes, including dominant CRD, RP and dominant as well as recessive LCA, in which marked retinal degeneration is already evident at birth." (PMID 25650393, 2015). "These mouse models will allow for the testing of novel therapeutic strategies for retinal diseases caused by CRX mutations." (PMID 24516401, 2014). "Thus, elucidation of the molecular mechanisms of CRX effector domain truncating mutations will advance our understanding not only of CRX-linked retinal diseases but also of more general cellular processes such as mRNA surveillance pathways." (PMID 38414750, 2024). "We found that retinal disease-related genes, most of which are crucial to photoreceptor functions, were efficiently expressed in PBMCs transduced with CRX via SeV vectors." (PMID 27170256, 2016). "We found that retinal disease-related genes were efficiently detected in CRX-transduced cells, most of which are crucial to photoreceptor functions." (PMID 27170256, 2016). "Transduction of RAX1 and NeuroD1 in addition to CRX and modification of the differentiation medium facilitated induction of a greater variety of retinal disease-related genes." (PMID 27170256, 2016). "Recognising distinctive phenotypes, such as the distinct pattern of nasal degeneration observed in some cases of CRX-associated retinal disease, which is not typically seen in other forms of inherited retinal disease, is important." (PMID 39632990, 2025). "CABP4, a retinal disease gene and direct transcriptional target of CRX showed a similar trend." (PMID 33513359, 2021). "In one example variants in a known disease gene for early onset retinal disease (CRX), caused a later onset retinal phenotype not previously seen with CRX variants." (PMID 28874452, 2017). "Furthermore, we found a greater variety of retinal disease-related genes by modification of culture conditions compared to that observed in CRX-transduced PBMCs." (PMID 27170256, 2016). "Moreover, by modification of the culture conditions including additional transduction of RAX1 and NEUROD1, we found a greater variety of retinal disease-related genes than that observed in CRX-transduced PBMCs." (PMID 27170256, 2016). "Surprisingly, whereas heterozygosity of specific CRX mutations in humans can cause severe retinal disease, Crx+/− mice develop normal photoreceptors that do not degenerate." (PMID 25650393, 2015). "Several retinal disease-related genes absent in cells transduced with CRX alone were also significantly detected in cells transduced with CRX before NeuroD1 or those transduced with RAX1+CRX before NeuroD1 in a modified medium containing Activin A, Dkk, and Lefty2 or the RPE-conditioned medium." (PMID 27170256, 2016).
Macular dystrophy (8 papers, 2021 to 2025). Macular dystrophy is a nonspecific term for retinal degeneration, generally confined to the macula, usually presumed of genetic origin. "We present 3 members of a family with macular dystrophy, originally diagnosed as Stargardt disease, with a significantly variable age at onset, caused by a heterozygous mutation in CRX." (PMID 33836713, 2021). "Heterozygous individuals in ABCA4 disease and control cohort harboring rare variants in macular dystrophy genes CDHR1, CHM, CRX, ELOVL4, PROM1, PRPH2, ROM1." (PMID 35353811, 2022). "Heterozygous individuals in ABCA4 disease and control cohort harboring variants with MAF<0.005 and CADD score >25, in each macular dystrophy gene CDHR1, CHM, CRX, ELOVL4, PROM1, PRPH2, and ROM1." (PMID 35353811, 2022). "Although all our patients were diagnosed clinically with STGD, the overlapping of phenotypes between different macular dystrophies and several stages of ABCA4-associated retinopathy could result in a misdiagnosis of STGD with mutations in phenocopying genes, such as PRPH2, ROM1, CRX, or RPGR." (PMID 33841504, 2021). "In this report of four patients with macular dystrophy and history suggestingStargardt-like disease, two patient’s phenotypes were related to AD genes(RIMS1 and CRX) and those of the other twopatients were related to AR genes (CRB1 andRDH12)." (PMID 36995812, 2023).
retinal dystrophies (8 papers, 2015 to 2025). "This study aimed to investigate the clinical characteristics of Korean patients with retinal dystrophy associated with pathogenic variants of cone rod homeobox-containing gene (CRX)." (PMID 37239417, 2023). "The subnetwork retrieved after querying for three retinal-specific transcription factors (shortest path between NRL and NR2E3, plus addition of CRX) allows showing their connection to other causative retinal dystrophy genes." (PMID 31712826, 2019). "The parafoveal hyperpigmented ring observed in Proband A resembles bull's-eye maculopathy (BEM), often seen in inherited retinal dystrophies such as those caused by POC1B, ABCA4, CRX, and GUCY2D mutations." (PMID 41293231, 2025). "Mutations in the CRX gene may be associated with various phenotypic presentations within the spectrum of inherited retinal dystrophies, and sometimes this may be probably related to the interaction of CRX with many other retinal genes." (PMID 38792980, 2024).
Blindness (5 papers, 2018 to 2024). Blindness is the condition of lacking visual perception defined as a profound reduction in visual perception. "A CRX mutation, which is the equivalent of a monoallelic knockout in humans, also constitutes a clear cause of blindness." (PMID 32831148, 2020). "Inherited retinal disorder (IRD) is a leading cause of blindness, and CRX is one of a number of genes reported to harbour autosomal dominant (AD) and recessive (AR) causative variants." (PMID 32533067, 2020). "Several previous studies indicated that defects of CRX or PDC might answer for photoreceptor degeneration, leading to cone swelling and loss of photoreceptor cells, and eventually causing blindness." (PMID 33874942, 2021).
autosomal dominant retinitis pigmentosa (4 papers, 2013 to 2024). Autosomal dominant retinitis pigmentosa (RP) is an autosomally dominant inherited retinal dystrophy leading to progressive loss of the photoreceptors and retinal pigment epithelium and resulting in blindness usually after several decades. "However, BG reported this patient to have a pathogenic deletion in CRX, which has been associated with autosomal dominant retinitis pigmentosa." (PMID 38892829, 2024). "There are at least five genes, RHO, NRL, NR2E3, CRX, and RP1, associated with both autosomal dominant retinitis pigmentosa (ADRP) and autosomal recessive retinitis pigmentosa (ARRP)." (PMID 25692141, 2015).
myopia (4 papers, 2022 to 2025). "CRX expression in the retinal cells was inhibited by light stimulation, a mechanism previously implicated in myopia development." (PMID 36137074, 2022). "Both SIX6 and CRX have previously been implicated in myopia development, however—as discussed later—the two novel, rare missense variants identified here had much larger effects than those identified in previous GWAS investigations." (PMID 35022715, 2022).
cone-rod dystrophy 2 (3 papers, 2009 to 2025). Any cone-rod dystrophy in which the cause of the disease is a mutation in the CRX gene. "Mutations in the human CRX gene lead to photoreceptor degeneration and the retinal diseases cone-rod dystrophy 2 (CORD2), Leber congenital amaurosis type VII (LCA7), and retinitis pigmentosa, late onset dominant." (PMID 19936203, 2009).
macular degeneration (3 papers, 2020 to 2024). Loss of vision in the central portion of the retina (macula), secondary to retinal degeneration. "While most mutations in CRX result in LCA7, other phenotypes including cone–rod dystrophy, RP and macular degeneration have been described." (PMID 32260251, 2020).
medulloblastoma (3 papers, 2009 to 2024). A malignant, invasive embryonal neoplasm arising from the cerebellum. "An interesting finding in this study is that CRX is expressed in a heterogeneous subpopulation of cells in four out of the ten medulloblastomas that were analyzed." (PMID 19936203, 2009). "The notable exception was medulloblastoma, 40% of which exhibited CRX expression in a heterogeneous pattern readily distinguished from that seen in retino-pineal tumors." (PMID 19936203, 2009). "Furthermore, we identified retina specific interphotoreceptor matrix proteoglycan 2 (IMPG2), phosducin (PDC) and prominin 1 (PROM1) as upregulated genes in the RB tumor group, which are all related to CRX expression in medulloblastoma." (PMID 39695086, 2024). "The fact that CRX is expressed by Group 3 medulloblastoma as well as most pineal tumours, and that Group 3 medulloblastoma and pineoblastoma are often histologically indistinguishable and share a poor prognosis despite intensive therapy, supports the idea of a molecular relationship between the two." (PMID 25412507, 2014). "Interestingly, four of ten medulloblastoma demonstrated a subpopulation of scattered cells with positive intranuclear CRX staining." (PMID 19936203, 2009). "The early rod precursor-specific transcripts, CRX and NRL were exclusively and strongly over-expressed by Group 3 medulloblastoma." (PMID 25412507, 2014).
pineoblastoma (3 papers, 2009 to 2017). Pineoblastoma is a rare, malignant type of supratentorial primitive neuroectodermal tumor (sPNET), found mainly in children (less than 10% of cases are reported in adults), and located in the pineal region of the brain but that can metastasize along the neuroaxis. "While this heterogeneous pattern of immunoreactivity is noteworthy, none of the cases demonstrated the robust, uniform pattern of CRX immunostaining most often seen in pineoblastoma." (PMID 19936203, 2009). "Consistent with our results showing that the frequency and intensity of expression of CRX protein is similar in pineoblastoma, PPTID and pineocytoma, CRX was not among the list of genes which discriminated classes of pineal parenchymal tumors." (PMID 19936203, 2009).
Bull's eye maculopathy (2 papers, 2023 to 2025). Progressive maculopathy characterized by concentric regions of hyper- and hypopigmentation, with an initial foveal sparing and whose appearance is said to resemble the central target of a dart board. "Pathogenic variants downstream of the homeodomain of the CRX gene are present as RP, LCA, and CORD, whereas pathogenic variants within the homeodomain are mainly present as CORD or MD with bull’s eye maculopathy." (PMID 37239417, 2023). "Mutations downstream of the homeodomain of the CRX gene are present as RP, LCA, and CORD, whereas mutations within the homeodomain are mainly present as CORD or MD with bull’s eye maculopathy." (PMID 37239417, 2023).
hyperopia (2 papers, 2016 to 2025). A refractive error in which rays of light entering the eye parallel to the optic axis are brought to a focus behind the retina, as a result of the eyeball being too short from front to back. "Hyperopia is common in some IRDs including AD BEST1-retinopathy, RS1 and some LCA genotypes (in the current cohort: AIPL1, ALMS1, CEP290, CRB1, CRX, TULP1)." (PMID 41465105, 2025).
pineal tumors (2 papers, 2009 to 2014). "Given its restricted expression and functional relevance in pineal and retinal cell lineages we sought to more comprehensively establish whether CRX might serve as a robust TF marker for research and digansotic evaluation of retino-pineal tumors." (PMID 19936203, 2009).
X-linked retinoschisis (2 papers, 2023 to 2026). A genetic ocular disease that is characterized by reduced visual acuity in males due to juvenile macular degeneration. "Here, we delve into three distinct categories that classically manifest electronegative ERG: congenital stationary night blindness (CSNB), X-linked retinoschisis (XLRS), and cone dystrophy due to CRX gene mutation." (PMID 37835784, 2023).
-cone dystrophies (1 paper, 2020). "Gene therapy strategies that aim to preserve and prevent cone loss in rod-cone dystrophies are of great interest and in line with this broad treatment approach, we generated an rAAV.CRX construct." (PMID 32842706, 2020).
alcohol abuse (1 paper, 2018). The use of alcoholic beverages to excess, either on individual occasions ("binge drinking") or as a regular practice. "Interestingly, the variants identified in EPS8L3 (rs148185176), MYH7, CRX (rs139340178), and SELENOO, were also present in two relatives with alcohol abuse (individuals 6 and 18)." (PMID 30379966, 2018).
autosomal recessive cone-rod dystrophies (1 paper, 2008). "Seven genes reported to be associated with autosomal recessive cone-rod dystrophies (crd), ABCA4, RDH5, CORD8, CORD9, RPGRIP1, CRX and GUCY2D were therefore included in the study." (PMID 18593457, 2008).
cyst (1 paper, 2009). A sac-like closed membranous structure that may be empty or contain fluid or amorphous material. "Gliotic regions composing the cyst wall were negative for intranuclear CRX immunostaining as were inflammatory cells and endothelial and smooth muscle cells composing blood vessels." (PMID 19936203, 2009).
germ cell tumor (1 paper, 2009). A benign or malignant, gonadal or extragonadal neoplasm that originates from germ cells. "A panel of lineage specific transcription factors including CRX (pineal), OLIG2 (diffuse gliomas) and OCT4 (germ cell tumors) were utilized to “decode” the lineage of the tumor." (PMID 19936203, 2009).
glaucoma (1 paper, 2021). Increased pressure in the eyeball due to obstruction of the outflow of aqueous humor. "These 13 glaucoma-associated genes can be divided into three functional groups: phototransduction-related genes (GNGT1, OPN1SW, PDE6A, PDC, CRX, CNGB1, GUCY2F), glutamate receptor (GR) genes (GRIN2B, GRIK3, GRIK4), and 5-hydroxytryptamine receptor (HTR) genes (HTR1A, HTR1E, HTR7)." (PMID 33874942, 2021).
glioma (1 paper, 2009). A benign or malignant brain and spinal cord tumor that arises from glial cells (astrocytes, oligodendrocytes, ependymal cells). "In this case CRX and the germ cell transcription factor OCT4 were negative and showed no intranuclear reactivity in tumor cells, while OLIG2 exhibited strong nuclear staining consistent with a high-grade glioma arising principally in the pineal region." (PMID 19936203, 2009).
hyperglycaemia (1 paper, 2025). "Notably, transcription factors critical for photoreceptor development, such as CRX and NRL, remained unchanged, suggesting that hyperglycaemia selectively impairs photoreceptor terminal differentiation and function rather than their initial specification." (PMID 41419458, 2025).
lung carcinoma (1 paper, 2017). "CRX, TCF3, and GABP were predicted as novel putative transcription factors in lung cancer." (PMID 28592245, 2017).
optic atrophy (1 paper, 2021). A disorder characterized by loss of optic nerve fibers. "Owing to the unusual clinical presentation in III:3 and the nonsegregating optic atrophy and distinct phenotype in III:2, the CRX variant was thought to not account for the full phenotype and thus the family was recruited into the 100KGP for further investigation." (PMID 34905022, 2021).
Pigmentary retinopathy (1 paper, 2022). An abnormality of the retina characterized by pigment deposition. "Thus, it is plausible that CRX function is maintained within our proband, accounting for the lack of pigmentary retinopathy on clinical exam." (PMID 35422034, 2022).
pineal parenchymal tumors (1 paper, 2009). "CRX expression was also evaluated by immunohistochemistry in 13 pineal parenchymal tumors that were classified according to WHO criteria." (PMID 19936203, 2009).